PPARG (peroxisome proliferator activated receptor gamma)
Diseases named in the same sentence as PPARG in open-access papers (continued):
Sharing a sentence is not in itself a finding about the gene and the disease.
Obesity (continued). "In the cell test, the anti-obesity abilities of DOW-RMD in inhibiting PPARγ and C/EBPα expression in differentiation and lipoprotein lipase activity in lipogenesis were contributed to by the DOW-increased monascin and ankaflavin levels and the ions of DOW, respectively." (PMID 24132179, 2013). "Taken together, these results suggest that CPE and CFSE administration could ameliorate obesity and related metabolic disorders in HF diet-induced obesity mice probably through the inhibition of PPARγ and LXRs gene expressions." (PMID 24317433, 2013). "PPARγ expression reduction was observed in obesity subjects." (PMID 23342006, 2013). "Therefore, the potential therapeutic usefulness of PPARα and PPARγ activation in the control of obesity and diabetes-induced chronic (low-grade) inflammation has extensively been studied over the last couple of years using rodents." (PMID 23766760, 2013). "Our manuscript establishes how elevated FAs, as would be observed in the context of obesity, decrease PPARγ expression, which further prevents PPARγ transrepressional activity, further resulting in the upregulation of macrophage chemoattractant secretion by adipocytes." (PMID 22529965, 2012). "Recent evidence suggests that activation of CNS PPARα and/or PPARγ may contribute to weight gain and obesity." (PMID 22916190, 2012). "Our in vitro experimental data indicate that SBM may be a potent modulator of obesity by repressing the PPARγ-regulated adipogenesis pathway and augmenting the TNFα-induced lipolytic and apoptotic pathway." (PMID 22292054, 2012). "Based on the inhibition of obesity and hyperlipidemia, we tested whether EK acts on PPARγ, α, β/δ and LXRα and LXRβ, which are drug targets for metabolic syndromes." (PMID 23226556, 2012). "Our data suggest that rhein improves metabolic disorders through the PPARγ antagonism and rhein may be a potential candidate for obesity therapy." (PMID 23049539, 2012). "Reporter assay and gene expression analysis verified that rhein inhibited PPARγ transactivity and might play a role in prevention and treatment of obesity and metabolic diseases." (PMID 23049539, 2012). "Therefore, while these studies demonstrate that miR-130a/b play a key role in post-transcriptional regulation of PPARγ expression in adipogenesis and obesity, additional work is required to clarify the role of miR-27a/b in these processes." (PMID 22991504, 2012). "A model of SGA rat offspring has been shown to exhibit increased adipose tissue expression of a key adipogenic transcription factor, peroxisome proliferator-activated receptor gamma (PPARγ), and increased fatty acid de novo synthesis during the nursing period, prior to onset of obesity." (PMID 22726273, 2012). "It has been shown that PPARγ antagonists can prevent and treat HF diet-induced obesity." (PMID 23320036, 2012). "Conversely, suppression of PPARγ signaling by its antagonist may inhibit adipocyte differentiation, reduce body weight, and improve metabolic disorders in C57BL/6 mice, suggesting that PPARγ is a potential target for obesity therapy." (PMID 23049539, 2012). "Recent evidence suggests that CNS activation of PPARα and/or PPARγ may contribute to weight gain and obesity." (PMID 22916190, 2012). "The identification of PPARs as key regulators of diverse aspects of energy homeostasis has made them attractive pharmacological targets to treat metabolic diseases such as lipid disorders (drugs targeting PPARα or -δ), T2D (drugs targeting PPARγ), and obesity (drugs targeting PPARδ)." (PMID 22745632, 2012). "On the contrary to what was observed in obesity, PPARγ expression is decreased in visceral adipose tissues of mouse models of diabetes (db/db), which may directly affect adipocyte differentiation and/or function." (PMID 22991504, 2012). "SGA newborns demonstrate increased PPARγ expression prior to the onset of obesity." (PMID 22726273, 2012).
Obesity (continued). "Other genes such as MC4R, leptin and leptin receptor, Ghrelin (GHRL), peroxisome proliferator-activated receptor gamma (PPARG), oxytocin receptor (OXTR), prohormone convertase-1 and proopiomelanocortin have been implicated in human obesity and will be discussed elsewhere in this journal issue." (PMID 22043167, 2011). "Using our second mouse model of obesity, the influence of a high fat diet on miRNA expression could be analyzed either physiologically or under conditions when PPARγ activity was reduced." (PMID 21731698, 2011). "As the pathways identified in our POKO islets are involved in the failure of β-cell function, our results indicate an important role of PPARγ in islets, modulating the adaptive response of β-cell mass to increased metabolic demands imposed by obesity and insulin resistance." (PMID 22208362, 2011). "A study of PPARγ+/− mice shows that appropriate reduction in PPARγ expression prevents obesity induced by a high-fat diet; therefore, inhibition of PPARγ expression may be an effective way to prevent obesity." (PMID 21760932, 2011). "Importantly, antagonism of PPARγ using a synthetic ligand suppresses the increased adiposity observed in HF induced obesity." (PMID 21695273, 2011). "Despite low C/EBPα and PPARγ, fat cell size is usually increased in obesity." (PMID 20701600, 2010). "Interestingly emerging evidence indicates that the HO system suppresses different inflammatory events including macrophage infiltration and potentiate insulin sensitivity and glucose metabolism in obesity in a similar way as PPARγ." (PMID 20508722, 2010). "We aimed to characterise the possible longitudinal associations of common diabetes-susceptibility variants in the KCNJ11, PPARG, TCF7L2, IGF2BP2, CDKAL1, SLC30A8 and HHEX gene loci, with fasting glucose level; and of an obesity-associated variant in the FTO gene, with body mass index (BMI)." (PMID 20929593, 2010). "Our data indicate that NEFA appears to reciprocally regulate PPARγ and Wnt/β-catenin expression in stromal cells at the transition level, providing a mechanistic explanation for the association between HFD-induced obesity with increased marrow adipogenesis and increased bone loss." (PMID 21060836, 2010). "The rare allele of PPARG SNP rs3856806 has been linked with not only coronary artery disease progression, but also with pro-inflammatory cytokines (MMP9 and TNFα), plasma homocysteine levels, and obesity." (PMID 20426853, 2010). "Despite emerging evidence for a role for Tusc5 in adipocyte function, robust WAT expression of the gene, and its regulation by PPARγ agonists in cultured adipocytes, it is not known if Tusc5 expression or activity is associated with obesity phenotypes." (PMID 20204174, 2009). "We tested the hypothesis that the TUSC5 gene is a bona fide PPARγ target and evaluated whether its WAT expression or single-nucleotide polymorphisms (SNPs) in the TUSC5 coding region are associated with human obesity." (PMID 20204174, 2009). "We also performed haplotype analyses to evaluate whether a particular combination of alleles could better explain the effect of PPARG genetic variability on CHD risk and assessed whether overweight and obesity could modulate this risk." (PMID 20016803, 2009). "It was previously demonstrated that the genetic effects of variants associated with either insulin secretion (like for GCK, KCNJ11 or TCF7L2) or insulin action (for ENPP1, ADIPOQ or PPARG) may be modulated by the obesity status or adiposity." (PMID 19368707, 2009). "To further characterize this correlation, we next analyzed methylation of the PPARγ promoter in adipocytes from a mouse model of diet-induced obesity (DIO), which are WT mice fed with a high-fat diet from 4 to 20 weeks old that subsequently present a type 2 diabetes-like phenotype." (PMID 19589179, 2009).
Obesity (continued). "This large case-control study further supports the hypothesis that the T2D risk contribution of ENPP1, ADIPOQ, PPARG and TCF7L2 SNPs may be modulated by obesity status." (PMID 18498634, 2008). "ENPP1, ADIPOQ, PPARG and TCF7L2 single nucleotide polymorphisms (SNPs) have previously been associated with T2D and have shown variable significance amongst different classes of obesity." (PMID 18498634, 2008). "In this way, PPARG activation may improve female infertilityexacerbated by obesity and insulin resistance." (PMID 18309368, 2008). "Since synthetic PPARα and PPARγ agonistsindependently ameliorate obesity-induced inflammation, agoniststhat activate both PPARα and PPARγ (the so-calleddual PPARα/PPARγ agonists) might be even moreeffective." (PMID 17389767, 2007). "As PPARg2 is the PPARg isoform regulated in response to nutrition and obesity, we hypothesised that PPARg2 would only become essential for adipose tissue function in the face of positive energy balance." (PMID 17465682, 2007). "In just over a decade, PPARγ has evolved from modestbeginnings as a simple regulator of adipogenesis to become a keytherapeutic target in the fight against the 21st century epidemicsof obesity, insulin resistance, and the metabolic syndrome." (PMID 17389771, 2007). "We speculatethat obesity may induce the expression of PPARγ isoformsin growth plate chondrocytes, resulting in phenotypic changes thatinterrupt normal skeletal maturation at the growth plate throughinterference with thyroid hormone signaling." (PMID 17259668, 2006). "Since PPARγ agonists increase insulin sensitivity but promote adipogenesis, decreased activity of PPARγ in adipose tissue could explain why CLA reduces obesity but increases insulin resistance." (PMID 15642120, 2005). "Therefore, the maintenance of Th2 responses by PPARγ seems to prevent the amplification of a more pathological Th17‐biased inflammation, suggesting PPARγ agonists could be used for targeting obesity‐related allergic diseases." (PMID 40329860, 2025). "Consequently, targeting PPARγ deacetylation could provide a favorable therapeutic option to counter against diabetes, obesity, and their comorbidities." (PMID 41473291, 2025). "Additionally, studies have documented the effect of moringa on adipogenesis by regulating C/EBPα, adiponectin, FABP4, and PPARγ, as well as augmenting thermogenesis in adipose tissue, which testifies to the anti-obesity effect of moringa and supports the current findings." (PMID 41011207, 2025). "However, excessively high concentrations of SCFAs may paradoxically exacerbate obesity by promoting adipocyte proliferation—via PPARγ-mediated lipid accumulation and AMPK signaling suppression." (PMID 40852190, 2025). "The concentration of falcarindiol evaluated in this study is believed to be related to its biological effects, but further in vivo and clinical studies are needed to determine whether falcarindiol exerts an anti-obesity effect by activating PPARγ and inducing adipocyte differentiation in the body." (PMID 40529474, 2025). "Moreover, it has been reported that a reduction in the differentiation capacity of preadipocytes in obesity, which may occur as a consequence of PPARγ inhibition in preadipocytes, leads to decreased adipogenesis." (PMID 40871639, 2025). "Given the established role of SIRT1 in mitochondrial biogenesis and the involvement of PPARγ/Lipin-1 in lipid handling, this pathway may contribute to the balance between lipid storage and oxidation, with potential implications for obesity, dyslipidemia, and insulin resistance." (PMID 41007632, 2025). "Our findings reveal cell-state dependent roles of ZBTB9 in adipocytes, identifying a new molecule that regulates adipocyte biology as both a positive and negative regulator of PPARγ signaling depending on the cellular context, and thus may be important in the pathogenesis of obesity and T2D." (PMID 39542250, 2024).
Obesity (continued). "However, it is acknowledged that while the PPARα to a lesser degree, and PPARγ in particular are key coordinators in the adipogenesis metabolic axis, this is not the entire mechanistic picture towards adverse adipogenicity leading to obesity." (PMID 39040675, 2024). "It is these effects that cause obesity-induced thermogenesis: in BAT and inguinal WAT, β3AR signaling induces PRDM16 and PGC1α via the β3AR–cAMP–PKA pathway and increases UCP1 expression in mice; PPARα and PPARγ are also involved in heat production through this signaling pathway." (PMID 39796158, 2024). "In addition, neuron-specific PPARγ KO females displayed alterations in ovarian cycle length and LH levels, as well as hemorrhagic corpora lutea in the ovaries; yet, they were protected from obesity-induced leptin resistance and ovarian cycle irregularities." (PMID 39290326, 2024). "In addition, to our study showing the potency of M. paniculata in treating obesity, further research is needed to confirm the results using the standard analog drugs PPARG and EP300 and to measure lipid accumulation and expression in brown adipose tissue via in vitro assay." (PMID 39208245, 2024). "Therefore, additional studies are needed to determine exactly whether the activated PPARγ pathway induces or inhibits autophagy during obesity." (PMID 39683397, 2024). "Thus, PPARγ activation by autophagy may be the mechanism by which autophagy induces obesity, and may become a future target for preventing obesity-associated autophagy during MetS." (PMID 39683397, 2024). "Additionally, although beta-sitosterol, α-amyrin, and phyllanthin were found not to interact with AKT1 and PPARG genes, they still showed potential for reducing the risk of obesity and warrant further exploration." (PMID 39409084, 2024). "In this context, our data showing down-regulation of PPARG, AP2, LEP and TNFA mRNA levels by Braco-19 treatment of differentiating ASCs suggest that targeting G4 motif might be beneficial against obesity-associated excessive lipid accumulation and inflammation." (PMID 37076894, 2023). "Thus, Twist1 may function as an anti-obesity factor during adipogenesis and this function is likely via the interaction between Twist1 and PPARγ." (PMID 37996425, 2023). "Animal studies have found that amidation-modified Apelin-13 might significantly reduce the average diameter of adipocytes, mRNA and protein expression of peroxisome proliferator-activated receptor γ (PPARγ) levels and perilipin 1 (PLIN1), thereby improving the dyslipidemia caused by obesity." (PMID 38089606, 2023). "However, the role of PPARγ in the development of obesity-related cancer is still unclear." (PMID 37649895, 2023). "Complementary functional screens of target genes of causative methylation variations demonstrate novel effects on adipogenesis, PPARG signalling and adipocyte lipid handling, offering cellular mechanisms by which DNA methylation may promote obesity and its consequences." (PMID 37188674, 2023). "In the body, these AGEs can disrupt receptors and increase the risk of developing obesity in utero, and exposure to polycyclic aromatic hydrocarbon (PAH) alters methylation and increases the activity of the primary regulator of adipogenesis, peroxisome proliferator-activated receptor-gamma." (PMID 37240215, 2023). "However, it remains unclear how pathophysiologic PPARγ signaling during diet-induced obesity (DIO) or thermoneutral stimulation can specifically temper thermogenesis in white adipose depots." (PMID 37909330, 2023).
Obesity (continued). "Mechanistically, PPARγ2 levels were decreased in PER1/2-disrupted macrophages and restoration of PPARγ2 levels reduced the infiltration of pro-inflammatory macrophages in adipose tissue, suggesting that PPARγ may link the molecular clock genes and obesity-related inflammation." (PMID 37153549, 2023). "Therefore, obesity may be controlled by reducing adipogenesis through inhibition of PPARγ activity to negatively modulate preadipocyte differentiation." (PMID 36986539, 2023). "In addition, the lncRNA-MIR99AHG sponges miR-29b-3p to promote PPARγ-mediated regulation of preadipocyte differentiation, which may be involved in obesity." (PMID 37958699, 2023). "Furthermore, the combination of EH with coixol or stigmasterol shows anti-obesity effects by reducing the expression of adipogenic transcription factors such as C/EBPα and PPARγ through the successful inhibition of GR activity as transcription factors (TFs) in the nucleus." (PMID 37990123, 2023). "Indeed, PPARγ undergoes pronounced acetylation in obesity and aging." (PMID 37408258, 2023). "Therefore, increased syncytin-1 expression in subjects with increased BMI may result from increased muscle PPARγ, whose expression is reported higher in muscle of humans characterized by obesity." (PMID 35444566, 2022). "Thus altogether, in our study effects of Se on PPARγ and CEBPα expression could indicate a restoration of epididymal fat adipocyte metabolic function during obesity." (PMID 35624758, 2022). "Indeed, PPARG may contribute to obesity by controlling food intake and appetite, not only through changes in insulin sensitivity, but also by regulating the transcription of the leptin gene, which is a key regulator of the central control of eating behavior." (PMID 36558537, 2022). "Relevant associations between metabolic parameters, lipid profile, and PPARG polymorphisms have though been found, even among studies that could not conclude that the analyzed gene variants represent an obesity/overweight risk." (PMID 36466447, 2022). "Therefore, the activation of the PPARγ/PGC-1α pathway may be a potential target for obesity treatment." (PMID 35647185, 2022). "Also, α-mangostin treatment upregulated liver AMPK, SIRT-1 and PPARγ showing that this compound could ameliorate obesity and liver steatosis by these pathways." (PMID 33499382, 2021). "Obesity is characterized by expansion of adipose tissue starting by adipocyte hyperplasia, mediated by the recruitment and proliferation of adipogenic precursors, mainly the peroxisome proliferator-activated receptor gamma (PPARγ), followed by adipocyte hypertrophy." (PMID 33430086, 2021). "In this cohort, a positive correlation between the PDK1/2 and PPARγ expression levels was noted, suggesting that like PPARγ expression, PDK1 and PDK2 expression might be implicated in the pathogenesis of human obesity." (PMID 34552205, 2021). "In conclusion, the current study revealed that papain treatment could inhibit obesity progression by regulating lipid accumulation and lowering blood lipid levels through the downregulation of adipogenic factors including PPARγ, C/EBPα, and SREBP-1 in HFD-induced obese mice and 3T3-L1 preadipocytes." (PMID 34576066, 2021). "Muscle aging is associated with diabetes and obesity, and in the present study, we compared the expressions of the FMOD and MSTN genes and those of genes related to muscle aging (Atrogin 1, Glb1), diabetes (RAGE, CD163) and intracellular lipid accumulation (CD36, PPARγ) in vivo and in vitro." (PMID 34440852, 2021). "Therefore, upregulation of PPARγ and C/EBPα is observed in the advanced stage of adipocyte differentiation and might be an effective target for the treatment of obesity." (PMID 34232916, 2021).